MPO (myeloperoxidase)
Diseases named in the same sentence as MPO in open-access papers (continued):
Sharing a sentence is not in itself a finding about the gene and the disease.
kidney damage (22 papers, 2014 to 2026). "The level of MPO was significantly inversely correlated with the glomerular filtration rate (Rs = −0.756, p = 1.8 × 10−6), indicating an association with kidney damage in SLE." (PMID 41465552, 2025). "However, the results of clinical studies regarding MPO functional polymorphism and risk factors of kidney damage seem to be controversial." (PMID 27127544, 2016). "Our study utilizing mass spectrometry revealed that, despite the lower accumulation of Cd in the kidney compared to the liver, exposure to Cd resulted in more pronounced kidney damage, as indicated by the detection of MPO." (PMID 40809692, 2025). "Camel milk (10 ml/kg) was administered to rats in a kidney damage model, and it regulated renal inflammation by suppressing myeloperoxidase (MPO), interleukin-1b (IL-1b), IL-18, and monocyte chemoattractant protein-1." (PMID 38183445, 2024). "Animal studies support these observations, showing that anti-MPO IgGs induce kidney damage with C3 deposits, while complement-depleted mice are protected from kidney damage." (PMID 38445024, 2024). "Treatment with CM (10 ml/kg/day; for 3 weeks by gavage) in cyclosporine-induced kidney damage in male Wistar rats, reduced MPO activity but increased the reduced/oxidized ratio of GSH and TAC." (PMID 35493477, 2022). "Nevertheless, MPO deficiency has been shown to delay CKD progression among 5/6 nephrectomized mice, thus confirming the role of MPO in kidney damage." (PMID 32823917, 2020). "Still, MPO-deficiency was recently demonstrated to retard the progression of CKD in 5/6 nephrectomized mice, thereby confirming the role of MPO in kidney damage." (PMID 27127544, 2016). "This study reports the outcome in a cohort of Central East European patients with pauci-immune crescentic glomerulonephritis, where MPO-ANCA specificity was predominant, and the kidney damage severe and associated with lung hemorrhage." (PMID 26123651, 2015). "Myeloperoxidase is an essential element of ethanol-induced kidney damage and dysfunction that distinguishes events that require leukocytic inflammatory infiltration from damage arising from local events that depend only on internal renal processes." (PMID 26720402, 2015). "Kidney damage was more acute in PR3-ANCA than in MPO-ANCA and N-ANCA, as reflected by the greater prevalence of oliguria (29 vs. 9 and 28%) and the proportion of patients needing dialysis at presentation (38 vs. 11 and 12%)." (PMID 27057255, 2014). "A more severe extent of kidney damage was implied in the MPO-ANCA subgroup." (PMID 36542276, 2023). "In this context, our group has previously demonstrated an increase in MPO levels in diabetic patients that correlated with the presence of nephropathy and leukocyte-endothelium interactions, thus pointing to the importance of MPO in conditions of oxidative stress." (PMID 27007571, 2016). "To address the question of whether Caspase-11/GSDMD played a vital role in NETs generation in hyperuricemic nephropathy, we accessed the expression of myeloperoxidase (MPO) and histone H3 (H3) in the kidney tissue from Gsdmd−/− mice, Caspase-11−/− mice, and WT control mice." (PMID 38436813, 2024). "The infiltration of MPO‐positive cells, a neutrophil‐derived protein, was significantly reduced by NAM in adenine‐induced nephropathy." (PMID 41324413, 2025). "The study found that WIT effectively reduced renal MPO activity and NF-kB, IL-1β, TNF-α, and IL-6 levels in DOX-induced kidney damage." (PMID 40006061, 2025). "Analyses of neutrophil elastase and myeloperoxidase in plasma and urine suggest that neutrophils are activated in adenine-induced nephropathy, but the production of NETs seems not to be directly involved in the pathogenesis of this CKD model." (PMID 42247428, 2026). "However, use of the anti-Ly6G neutralizing antibody of neutrophils prevented the exacerbated kidney damage induced by rmNGAL, as well as resulting in lower renal MDA, MPO and neutrophil elastase levels." (PMID 37848438, 2023).
kidney damage (continued). "In addition, Myeloperoxidase (MPO) was a specific marker of local neutrophil accumulation, which indicated the extent of kidney damage." (PMID 33597892, 2020). "Finally, none of these associations were detectable in myeloperoxidase-ANCA GN, implying different modes of kidney damage." (PMID 36542276, 2023). "However, pretreatment with kaempferol decreases myeloperoxidase (MPO) activity and the release of proinflammatory cytokines, including TNF-α, thereby decreasing the kidney infiltration of leukocytes and alleviating kidney damage." (PMID 36552226, 2022).
liver fibrosis (22 papers, 2009 to 2025). "On the other hand, the druggable myeloperoxidase (MPO) gene is associated with the promotion of NASH-induced liver fibrosis, which later forms HCC." (PMID 39596661, 2024). "Adjusted logistic models assessed the associations of MPO with markers of kidney disease (estimated glomerular filtration rate) and liver fibrosis (NAFLD score > 0.676 or Fibrosis-4 [FIB-4] score > 2.67) across ASCVD risk (low < 7.5%; intermediate 7.5% to < 20%; high ≥ 20%)." (PMID 40210927, 2025). "Expression of Myeloperoxidase (MPO), an enzyme predominantly released by neutrophils, correlates with the presence of MASH in patients and murine livers fibrosis, and MPO deficiency or pharmacological inhibition protects against MASH-induced liver injuries in mice." (PMID 40670579, 2025). "Moreover, MPO deficiency appeared to attenuate the development of hepatic fibrosis as evident from reduced hydroxyproline levels (p<0.01)." (PMID 23285030, 2012). "High MPO was associated with markers of CKD and liver fibrosis in low to intermediate ASCVD risk and treated groups." (PMID 40210927, 2025). "Neutrophil secretion of myeloperoxidase (MPO) is directly involved in the hepatocyte apoptosis and in triggering hepatic stellate cell function, which will promote liver fibrosis." (PMID 38239291, 2023). "H&E staining showed extensive hepatocyte necrosis in the ACLF group, Sirius staining indicated liver fibrosis, and MPO immunohistochemistry showed massive neutrophil infiltration." (PMID 37708451, 2023). "In NASH patients, plasma myeloperoxidase (MPO) levels are higher, and MPO induces liver cell death and activation of HSCs, which contribute to liver fibrosis." (PMID 36248852, 2022). "The numbers of K19+ cholangiocytes, myeloperoxidase (MPO)-expressing neutrophils, and αSMA+ HSCs, and liver fibrosis (Sirius red staining) were significantly lower in C33-treated mice relative to vehicle-treated mice." (PMID 36042192, 2022). "Treatment with genistein decreased levels of inflammation mediators, including IL-6, TNF-α, and myeloperoxidase, through downregulation of NF-κB in alcohol- and CCl4-induced liver fibrosis in rats." (PMID 25897319, 2015). "Prospective studies are warranted to assess whether high MPO levels identify persons at risk for CKD and liver fibrosis who may benefit from preventive strategies." (PMID 40210927, 2025). "In ob/ob mice, hepatic MPO decline may disrupt this feedback loop, leading to reduced hepatic fibrosis." (PMID 39832399, 2025). "The role of myeloperoxidase (MPO) in the progression of liver fibrosis has also been demonstrated." (PMID 39882525, 2024). "QE could significantly reduce the levels of MPO and NE, further verifying the effectiveness of QE in inhibiting neutrophil infiltration in liver fibrosis." (PMID 38943679, 2024). "The observed relationship between LDG MPO+ and APRI suggests that assessment of the diagnostic role of LDG in the process of liver fibrosis could be promising, and further research on this issue is warranted." (PMID 35456267, 2022). "Consistently, our in vivo studies showed that inhibition of IL-1β level with caspase-1 inhibitor dramatically reduced MPO activity in the liver and ameliorated liver fibrosis in BDL mouse model, suggesting an important role of IL-1β in triggering tissue inflammation and fibrosis during cholestasis." (PMID 27924062, 2016). "Assessment of inflammatory markers, such as the percentage of LDG and the percentage of LDG expressing MPO, may be helpful in assessing the phenomenon of an increased systemic inflammatory response and in assessing liver fibrosis (LC, Liver cirrhosis), which is inherent in liver decompensation." (PMID 35456267, 2022). "The involvement of enzymes such as neutrophil elastase (NE) and myeloperoxidase (MPO) in myocardial and liver fibrosis remains poorly understood." (PMID 40109341, 2025).
liver fibrosis (continued). "In line with this notion, genetic knockout or therapeutic inhibition of myeloperoxidase (MPO), one of the primary ROS-producing enzymes in neutrophils, reduces high-fat and high-cholesterol-induced liver fibrosis in mice." (PMID 38137437, 2023). "Similarly, dapagliflozin treatment at a dose of 1 mg/kg/day decreased hepatic ROS production of myeloperoxidase (MPO) and F4/80, thus ameliorating serum ALT levels and hepatic fibrosis." (PMID 35328527, 2022). "This study also reported that pharmacological inhibition of MPO through treatment with AZM198, an MPO inhibitor, could repress NASH progression and liver fibrosis induced by feeding a high-fat, high-cholesterol diet (HFHCD)." (PMID 34707573, 2021). "Finally, neutrophil elastase was also found to be increased in early stages of MAFLD, as well as neutrophil-derived myeloperoxidase (MPO), a molecule that specifically promote NASH-induced liver fibrosis in both animal models and human settings." (PMID 34899679, 2021).
gout (21 papers, 2011 to 2025). A condition characterized by painful swelling of the joints, which is caused by deposition of urate crystals. "The effects of SMWW and SMWE on swelling, pain, and inflammation in gouty arthritis were investigated by measuring affected limb swelling and weight-bearing, as well as by enzyme-linked immunosorbent assays, to assess the levels of proinflammatory cytokines and myeloperoxidase (MPO)." (PMID 33535406, 2021). "CXCL5 neutralizing antibody significantly reduced neutrophil and macrophage infiltrations in ankle joints of gout model mice, indicated by immunostaining and myeloperoxidase (MPO) assay." (PMID 38627393, 2024). "In gouty arthritis, neutrophils are recruited and attempt to phagocyte urate crystals, which can be oxidized via MPO." (PMID 38474000, 2024). "In gouty arthritis model mice, Simiao Decoction can effectively reduce the serum UA levels, reduce myeloperoxidase (MPO), XOD, and adenosine deaminase (ADA) activities, and relieve gout-related symptoms such as foot swelling and pain." (PMID 36034697, 2022). "With the criteria of unique peptides ≥ 2, 25 proteins were found highly expressed in gout uniquely, lysozyme C, alpha-1-acid glycoprotein 1, lactotransferrin, protein S100-A9, and myeloperoxidase included." (PMID 35359923, 2022). "The IF microscopy data were confirmed by measuring MPO/DNA complexes in the supernatant of neutrophils that were stimulated with activated human PLTs and gout SF." (PMID 32203195, 2021). "As previously reported, we found that MSU crystals can induce NET formation, as detected by immunofluorescence confocal microscopy and the detection of MPO-dsDNA in the synovial fluid of patients with gout." (PMID 33741037, 2021). "The proportion of CD14+ macrophages was significantly and inversely correlated with levels of MPO-dsDNA complex in the synovial fluid of gout patients." (PMID 33741037, 2021). "This significant correlation between the MPO and histone related to gout is similar with our established findings that MPO, histone H2A and histone H2B were significantly increased in AG, RG and AHU compared with the CTL." (PMID 34635120, 2021). "Specific to gout, MPO activity in articular joint tissues increased and has been previously correlated with neutrophil influx in a mouse model of crystal-induced inflammation." (PMID 30157934, 2018). "Peripheral PMNs from patients with gout released NETs, determined by co-staining with MPO and DAPI, when incubated for 3 h in a less prominent way compared to those observed in synovial fluid cells." (PMID 22195044, 2011). "In this study, similar results were revealed showing the decreased relative abundance of Lachnospiraceae and the significantly negative correlation between the relative abundance of Lachnospiraceae and the levels of UA, IL-1β, IL-6, TNF-α, MPO activity, and purine metabolism in mice with gout." (PMID 35145506, 2022). "In our study, injection of MSU crystals and feeding with HFD caused a decrease in the relative abundance of Bacteroides, which was significantly negatively correlated with the levels of UA, IL-1β, IL-6, TNF-α, MPO activity, and purine and pyrimidine metabolisms in mice with gout." (PMID 35145506, 2022). "In gouty arthritis, neutrophils undergo a process of neutrophil extracellular traps (NETs) consisting of DNA, histones, and neutrophil granules (including neutrophil elastase and MPO) to respond to stimulation by MSU crystals." (PMID 34564665, 2021). "Furthermore, the proportion of CD14+ cells was inversely correlated with the levels of the MPO-dsDNA complex in the synovial fluid of gout patients." (PMID 33741037, 2021). "Furthermore, MPO activity was significantly higher in mice with gouty arthritis than in the control group (indicating an influx of neutrophils and acute inflammation), and both JGTW and JGTE induced a decrease in the activity of this enzyme." (PMID 33371241, 2020).
gout (continued). "In addition, JGT efficiently downregulated MSU crystal-induced swelling and pain and contrasted inflammation by suppressing pro-inflammatory cytokines (IL-1β, TNF-α, and IL-6) and MPO activity in a gouty arthritis mouse model." (PMID 33371241, 2020). "When we measured the levels of the MPO-dsDNA complex, which indicates the release of NET, in the synovial fluid of patients with acute gout, the levels were significantly higher in gout patients than those in OA patients." (PMID 33741037, 2021). "Simiao decoction has the effect of reducing blood uric acid levels, reducing myeloperoxidase (MPO), xanthine oxidase (XOD), adenosine deaminase (ADA) activity, and alleviating gout-related symptoms (such as foot swelling and pain)." (PMID 34721646, 2021). "Concentrations of MPO, a marker of neutrophil activation that is also associated with increased cardiovascular risk, were unaffected by colchicine+XOI treatment, indicating that not all aspects of inflammation may be modulated with initiating treatment in gout." (PMID 32653044, 2020). "Treatment with anakinra, a recombinant IL-1 receptor antagonist, partially inhibited NET production, determined by co-staining with MPO and DAPI, from control PMNs treated with synovial fluid from patient with gout." (PMID 22195044, 2011). "In addition, we showed that CD14+ macrophages from the synovial fluid of patients with gout can engulf MSU crystal-induced NETs, as evidenced by NE and MPO or SYTOX Green uptake in confocal microscopy or flow cytometry, respectively." (PMID 33741037, 2021). "In addition, the correlations between CD14+ cells, MPO-dsDNA complexes, and expression of pro- and anti-inflammatory cytokines were analyzed in the synovial fluid CD14+ macrophages of patients with gouty arthritis." (PMID 33741037, 2021). "Furthermore, MPO activity was significantly elevated in mice with gouty arthritis, compared to the control group (indicating an influx of neutrophils and acute inflammation), while both SMWW and SMWE effectively decreased MPO activity." (PMID 33535406, 2021). "Given the established roles of MPO in hypochlorous acid generation and vWF in NET stabilization, these data suggest that QFHZ might attenuate gout recurrence by indirectly influencing NET-related inflammation." (PMID 41190022, 2025). "However, in a gouty arthritis animal model, SMWE more efficiently downregulated MSU-crystal-induced swelling and pain, and it exerted anti-inflammatory effects by suppressing proinflammatory cytokines (IL-1β, TNF-α, and IL-6) and MPO activity." (PMID 33535406, 2021).
viral infection (20 papers, 2005 to 2025). "It has been observed that virus infection causes changes in the form of statistically significant increases in the activity of MPO and LZM concentration, while in the case of LZM activity only statistically significant decreases were noted." (PMID 32899838, 2020). "Western blot analysis of NET-related proteins in lung tissue revealed significant increases in MPO and Cit-H3 protein levels after viral infection compared to those in the control group." (PMID 40666504, 2025). "We also analyzed genes associated with formation of NETS34,35: ELANE (neutrophil elastase) and MPO (myeloperoxidase) were elevated in MIS-C in comparison with viral infection (ELANE only) and KD." (PMID 39300098, 2024). "If type I immunity is triggered (viral infection), it is expected there would be a higher macrophage and lower neutrophil response (potentially more neopterin, less calprotectin/myeloperoxidase)." (PMID 38432562, 2024). "Our results of the histological analysis showed that upon viral infection, the MPO‐positive activated neutrophils had infiltrated in the lungs of the mid‐aged mice more than those that had infiltrated the lungs of young mice." (PMID 38098255, 2024). "At 3 days after primary infection with BA.2, a few CD3+ T cells and some myeloperoxidase ([MPO]; present in the granules of neutrophils and monocytes)-positive cells were seen at viral infection sites within the upper respiratory tract." (PMID 36633406, 2023). "Viral infection induces reactive oxygen species (ROS), which, in turn, stimulates myeloperoxidase (MPO), which, in turn, triggers the production of NE." (PMID 36851766, 2023). "For quick immunomagnetic detection of myeloperoxidase (MPO) (a biomarker indicating viral infection), an electrochemical lateral flow device has been developed." (PMID 35599642, 2022). "In this study, we found a significant correlation of MPO levels at 24 months of age with the total number of bacterial and viral infections in each child." (PMID 33886672, 2021). "We quantified MPO levels in fecal specimens and determined the correlation of fecal MPO levels at 24 months of age with the total number of bacterial and viral infections in each child over that period." (PMID 33886672, 2021). "The fold change in tissue factor-exposing microparticles in BAL fluid inversely correlated with the fold changes in eosinophil cationic protein and myeloperoxidase in BAL fluid after virus infection (r = -0.517 and -0.528 resp., both p = 0.01)." (PMID 24502801, 2014). "Neutrophil presence in the lung prior to secondary bacterial infection was evaluated by counting the number of Ly-6+ cells in lung tissue slides 14 days after viral infection and by measuring MPO concentrations in the corresponding whole lung homogenates." (PMID 23483993, 2013). "Compared to mock controls, either viral infection or rHMGB1 treatment alone led to MPO expression." (PMID 40367285, 2025). "We observed a significant correlation between the fecal MPO level in the children at 24 months of age with the total number of bacterial and viral infections, the total number of parasitic infections, and the total number of diarrheal episodes and diarrheal duration." (PMID 33886672, 2021). "Moreover, fold changes in eosinophil cationic protein and myeloperoxidase were both associated with the fold changes in FGT and TATc levels in BAL fluid after viral infection." (PMID 24502801, 2014). "In addition, the infiltration of neutrophils and monocytes that is associated with SARS-CoV-2 infection can activate myeloperoxidase (MPO), which is a peroxidase that participates as a mechanism of defense to decrease the viral infection, through the synthesis and liberation of HOCl." (PMID 38674128, 2024).